RNU6-630P (RNA, U6 small nuclear 630, pseudogene)
Gene: Small nuclear RNA gene on chromosome X (42,139,425 to 42,139,530, reverse strand). Ensembl gene ENSG00000212560.
Homologues: Orthologues: chimpanzee U6 (100% identical), macaque U6 (94% identical). Paralogues in human: RNU6-842P (86% identical), RNU6-1060P (85% identical), RNU6-486P (84% identical), RNU6-517P (84% identical), RNU6-701P (84% identical), RNU6-946P (84% identical), RNU6-1056P (83% identical), RNU6-166P (83% identical), RNU6-19P (83% identical), RNU6-24P (83% identical), RNU6-338P (83% identical), RNU6-42P (83% identical), and 1287 more.